PTK2B (protein tyrosine kinase 2 beta)
Diseases named in the same sentence as PTK2B in open-access papers (continued):
Sharing a sentence is not in itself a finding about the gene and the disease.
lung adenocarcinoma (1 paper, 2023). A carcinoma that arises from the lung and is characterized by the presence of malignant glandular epithelial cells. "Database analysis has also shown high expression of PTK2B in lung adenocarcinoma tissue, which is correlated with a good prognosis." (PMID 37622116, 2023). "The results of immunohistochemicals show that the expression of CD79B and PTK2B in lung adenocarcinoma is higher than tissue next to cancer." (PMID 37622116, 2023).
lymphopenia (1 paper, 2018). Reduction in the number of lymphocytes. "We also observed that lymphopenia was temporally associated with the upregulation of CCR2, LYN, PAK1, PTK2B, SRC, STAT3, which are involved in the chemokine signaling pathway." (PMID 30713538, 2018).
migraine (1 paper, 2026). "In PBMC T cells, co-expression modules capturing cytotoxic/activation and T-cell receptor signaling programs contained migraine-prioritized genes, including PTK2B, nominating immune activation circuitry as a component of genetic susceptibility." (PMID 41684036, 2026).
nicotine addiction (1 paper, 2017). "Ptk2b could potentially affect four signalling pathways: the chemokine, nicotine addiction, calcium and Jak-STAT signalling pathways." (PMID 29348887, 2017).
sinusoidal obstruction syndrome (1 paper, 2021). "Conditions such as viral reactivation, drug toxicity, tumoral organ infiltration, and sinusoidal obstruction syndrome among others may result in elevated PTK2B and SESN3 concentrations." (PMID 33082554, 2021).
squamous cell carcinoma (1 paper, 2018). A carcinoma arising from squamous epithelial cells. "Similarly, PTK2B has been reported to be involved in the CCR7‐mediated regulation of metastasis in squamous cell carcinoma and was found to be downregulated in our study." (PMID 29193607, 2018).
cancer (145 papers, 2005 to 2025). A tumor composed of atypical neoplastic, often pleomorphic cells that invade other tissues. "In conclusion, these findings highlight that MWDT exerts its anti-cancer effects by modulating the PTK2B/GPX4 signaling pathway." (PMID 41166024, 2025). "Emerging evidence highlights PTK2B's significance in tumorigenesis and progression, acting as an oncogene in various cancers such as cervical cancer, and breast cancer, where its overexpression correlates with tumor progression and poor prognosis." (PMID 41166024, 2025). "For example, the GLCRP including the lncRNA LINC00623 and the gene PTK2B participated in four cancer hallmarks, including evading apoptosis, insensitivity to antigrowth signals, self‐sufficiency in growth signals and sustained angiogenesis." (PMID 32202050, 2020). "CASS4 and PTK2B act as interacting partners regulating oncogenesis and metastasis, and are known to be active in the brain during development and in cancer." (PMID 29723294, 2018). "Reciprocally, these functions can better inform our understanding of the action of NEDD9, CASS4 and PTK2B in cancer." (PMID 25594051, 2014). "For historical reasons, the bulk of molecular characterizations of NEDD9, CASS4, and PTK2B have stressed their roles in cancer." (PMID 25594051, 2014). "Additionally, understanding the complex molecular interactions within the PTK2B/STAT3/GPX4 pathway is crucial for optimizing ferroptosis-based cancer therapies." (PMID 41166024, 2025). "Recent studies have shown that PTK2B plays an important role in many cancers." (PMID 37622116, 2023). "In PTC, PTK2B expression has been found to be upregulated, suggesting that it may contribute to the growth and survival of cancer cells." (PMID 37056339, 2023). "Intriguingly, NEDD9, CASS4, and PTK2B have been much studied as interacting partners regulating oncogenesis and metastasis, and all three are known to be active in the brain during development and in cancer." (PMID 25594051, 2014). "The described collection of functional relationships for NEDD9, CASS4 and PTK2B in AD is a generalizable approach of thinking about genotypes, phenotypes and ultimately functionality to understand diseases ranging from Alzheimer's to cancer." (PMID 25594051, 2014). "We identify STAT5B, H3F3A, and PTK2B as candidate cancer genes in T-ALL." (PMID 24367274, 2013). "Additionally, PTK2B is both the most frequently lost kinase and cancer-related gene, hemizygously deleted in 16/47 tumors (34%), and 12/18 cell lines (67%)." (PMID 16457699, 2005). "Therefore, we hypothesize that MWDT may promote ferroptosis through PTK2B, which may provide a new molecular mechanism for cancer treatment." (PMID 41166024, 2025). "For the analysis of survival probability, clinical data, and expression values for PTK2 and PTK2B genes (which code for FAK and Pyk2, respectively) in GBM tumors (provisional) were obtained from the cBioPortal for cancer genomics." (PMID 37686276, 2023). "These 50 drugs were also found to be validated in different cancer cell lines, such as dasatinib, captopril, leflunomide, and dextromethorphan targeting SRC, MMP2, PTK2B, and RAC1 hub genes, respectively." (PMID 35456223, 2022). "Tissue expression was confirmed to be significantly different in cancer vs. control samples for DNA2, MAOA, PARP1, TYR, and HDAC1 in the IST Online database and for PTK2B, MAOA, PARP1, and TYR in the GEPIA2 database." (PMID 34199192, 2021). "The LOAD-associated genes, cas scaffolding protein family member 4 (CASS4) and protein tyrosine kinase 2 beta (PTK2B), have been studied primarily for their roles in the directly cancer-relevant processes of migration and survival signaling." (PMID 29723294, 2018).
cancer (continued). "Interestingly, over the past two decades, several studies have identified roles for NEDD9, CASS4, and PTK2B in these processes, but this literature is typically underappreciated in the context of neurodegenerative diseases, in contrast to the focus on this signaling cluster in cancer and metastasis." (PMID 25594051, 2014). "PTK2B promotes tumorigenesis, migration, and invasion by activating several signaling pathways, including Wnt/β-catenin, PI3K/Akt, MAPK/ERK, and TGF-β/EGFR/VEGF, making it a promising target for cancer therapy." (PMID 41166024, 2025). "In cancer, discussion of action of the NEDD9-CASS4-PTK2B scaffolding and signaling axis almost invariably focuses on the regulation of cell migration and invasion, following the upregulation of NEDD9 and activation of PTK2B in many tumors." (PMID 25594051, 2014). "Finally, while the main focus of this review has been on the roles of NEDD9, CASS4, and PTK2B in LOAD, many of the LOAD-relevant processes can further highlight the significance of these proteins in cancer." (PMID 25594051, 2014). "PTK2B encodes the PYK2 protein, a member of the non-receptor tyrosine kinase of the focal adhesion kinase (FAK) family, which reportedly plays a pivotal role in carcinogenesis and cancer progression." (PMID 39272867, 2024).
tumor (143 papers, 1996 to 2025). "As a focal adhesion tyrosine kinase, PTK2B is aberrantly expressed in various tumors and is closely associated with tumor initiation and progression." (PMID 41166024, 2025). "In colony formation assays, overexpression of PTK2B partially counteracted the inhibitory effect of MWDT on tumor cell proliferation." (PMID 41166024, 2025). "The median survival probability in a cohort of patients with high gene expression versus low gene expression in tumor specimens was 12.94 months vs. 16.79 months (p = 0.009) for PTK2B and 12.58 months vs. 13.63 months (p = 0.0275) for PTK2." (PMID 37686276, 2023). "Recent comprehensive proteogenomic analysis of OC tissues revealed that autophosphorylation status of PTK2 (pY397) and PTK2B (pY402) was altered in tumor tissues." (PMID 31442208, 2019). "PTK2B, also referred to as Pyk2, promotes tumour proliferation through activation of MAPK signalling." (PMID 29518977, 2018). "In a small group of four patients with only skin aGvHD the mean value of SESN3 and PTK2B was 0.353 and 1.323, respectively (log SESN3/PTK2B copies/ml plasma)." (PMID 33082554, 2021). "Strikingly, further analysis of data within the TCGA database demonstrates significantly higher FAK (PTK), Pyk2 (PTK2B), and paxillin (PAX) mRNA in tumor samples compared to normal." (PMID 34031486, 2021). "Finally, immunohistochemical analysis of xenograft tumor tissues showed that MWDT treatment in vivo reduced the expression of PTK2B, p-STAT3, and GPX4, confirming the inhibition of this signaling pathway within the tumor microenvironment." (PMID 41166024, 2025). "Therefore, it is speculated that PTK2B and the JAK-STAT pathway may be in the same signaling network mediated by CCR7, working together to promote tumor progression." (PMID 41286896, 2025).
infection (18 papers, 2009 to 2024). The state of being infected such as from the introduction of a foreign agent such as serum, vaccine, antigenic substance or organism. "Consistently, immunoblotting results showed that the levels of phosphorylated STING, TBK1 and IRF3 stimulated by HSV1-GFP infection were decreased in Ptk2b-deficient cells compared with wild-type control cells." (PMID 37989995, 2023). "Conversely, PTK2B deficiency in THP1 cells remarkably attenuated STING oligomerization induced by HSV1-GFP infection." (PMID 37989995, 2023). "We observed that Ptk2b deficiency reduced the dimer of phosphorylated TBK1 induced by the infection of Sendai virus." (PMID 37989995, 2023). "Consistently, we observed that PTK2B deficiency reduced the formation of TBK1 granules induced by HSV1-GFP infection." (PMID 37989995, 2023). "In addition, we observed that the level of phosphorylation at Y591 induced by HSV1-GFP infection was much higher in wild-type RAW 264.7 cells than in Ptk2b-deficient cells." (PMID 37989995, 2023). "Moreover, we observed that wild-type TBK1, but not its mutants Y591F and Y591E, increased levels of phosphorylated IRF3 and Ifnb1 production induced by HSV1-GFP infection when PTK2B was co-expressed in TBK1-deficient MEF cells." (PMID 37989995, 2023). "Consistently, the levels of phosphorylated TBK1 and IRF3 induced by VSVΔM51-GFP infection were decreased in PTK2B-knockdown THP1 cells compared with those in the control cells." (PMID 37989995, 2023). "qPCR assays showed that Ptk2b deficiency significantly attenuated the mRNA levels of Ifnb1, Ifit1 and Cxcl10 stimulated by HSV1-GFP and VSVΔM51-GFP infection." (PMID 37989995, 2023). "qPCR results indicated that PTK2B overexpression significantly enhanced the mRNA levels of Ifnb1, Ifit1 and Cxcl10 induced by infection with HSV1-GFP or VSVΔM51-GFP in MEFs." (PMID 37989995, 2023). "qPCR results showed that Ptk2b deficiency dramatically reduced mRNA levels of Ifnb1, Ifit1 and Cxcl10 stimulated by HSV1-GFP or VSVΔM51-GFP infection." (PMID 37989995, 2023). "Immunoblotting results demonstrated that similar to the activation of TBK1 and IRF3, the activation of PTK2B was enhanced upon HSV1-GFP infection in a time-dependent manner." (PMID 37989995, 2023). "Consistently, Ptk2b deficiency reduced the levels of phosphorylated STING, TBK1 and IRF3 stimulated by HSV1-GFP infection." (PMID 37989995, 2023). "HSV1-GFP infection induced robust Tyr phosphorylation of TBK1 in wild-type RAW 264.7 cells, whereas Ptk2b deficiency reduced this effect." (PMID 37989995, 2023). "Furthermore, we provided in vivo evidence that PTK2B was required for efficient defense against the infection of HSV-1 or VSV by employing Ptk2b-knockout mice." (PMID 37989995, 2023). "We first tested whether HSV1-GFP infection induced the activation of PTK2B, which was detected by Y402-phosphorylated PTK2B in RAW 264.7 cells." (PMID 37989995, 2023). "In the present study, we found that overexpression of both wild-type PTK2B and its kinase-inactive mutant PTK2B(K457R) enhanced the aggregation of STING, and deficiency of PTK2B reduced the aggregation of STING stimulated by cGAMP and HSV1-GFP infection." (PMID 37989995, 2023). "Second, we knocked down Ptk2b in mouse macrophages RAW 264.7 cells and found that Ptk2b knockdown significantly impaired mRNA levels of Ifnb1, Ifit1 and Cxcl10 induced by infection with HSV1-GFP." (PMID 37989995, 2023). "Quantitative PCR (qPCR) analysis showed that PTK2B knockdown significantly attenuated the transcriptional levels of antiviral genes such as IFNB1, IFIT1 and CXCL10 induced by HSV1-GFP infection or by transfection with human telomeric DNA (HT-DNA)." (PMID 37989995, 2023). "Next, we conducted immunoblotting assays and found that PTK2B knockdown reduced the levels of phosphorylated STING, TBK1 and IRF3 induced by infection with HSV1-GFP." (PMID 37989995, 2023).
infection (continued). "PTK2B ASOs treatment downregulated levels of PTK2B protein, and reduced the levels of IFNB1 mRNA induced by the infection with HSV1-GFP or VSV-GFP." (PMID 37989995, 2023). "Consistently, we found that Ptk2b knockout decreased the levels of phosphorylated TBK1 and IRF3 induced by HSV1-GFP or VSVΔM51-GFP infection." (PMID 37989995, 2023). "Consistent results were obtained when PTK2B and wild-type TBK1 or its mutants were co-expressed in TBK1 knockout MEF cells, followed by HSV1-GFP infection." (PMID 37989995, 2023). "Of note, Co-IP results showed that HSV1-GFP infection markedly enhanced the association of TBK1 and PTK2B, but it had no apparent effect on enhancing the STING-PTK2B interaction." (PMID 37989995, 2023). "To determine whether PTK2B specifically mediates the innate immune response to DNA viruses, we infected PTK2B-knockdown THP1 cells or control cells with VSVΔM51-GFP and obtained similar results to those following HSV1-GFP infection." (PMID 37989995, 2023). "Consistently, PTK2B overexpression not only augmented the levels of phosphorylated STING, TBK1 and IRF3 induced by HSV1-GFP infection but also increased the levels of phosphorylated TBK1 and IRF3 induced by VSVΔM51-GFP infection." (PMID 37989995, 2023). "To further examine the interactions of PTK2B with STING, TBK1 and IRF3, we next performed endogenous Co-IP experiments with PTK2B antibody in RAW 264.7 cells with or without HSV1-GFP infection and found that PTK2B only pulled down STING and TBK1 regardless of the HSV1-GFP infection state." (PMID 37989995, 2023).
neurodegenerative disease (6 papers, 2014 to 2024). A disorder of the central nervous system characterized by gradual and progressive loss of neural tissue and neurologic function. "To date, although PTK2B and NEDD9 are abundant in neurites, a PTK2B-NEDD9-AURKA-NDEL1 axis has not been considered in neurite extension or neurodegenerative diseases." (PMID 25594051, 2014).
bacterial infection (3 papers, 2019 to 2025). "Protein Tyrosine Kinase 2 Beta (Ptk2ba) regulates protein tyrosine kinase activity and is implicated in human neutrophil migration and host defense response to bacterial infection." (PMID 35309302, 2022). "PTK2B participates in the innate immune response through interaction with IkappaB kinase β (IKKβ) and TANK-binding kinase 1 (TBK 1), and is critical for neutrophil degranulation and host defense against bacterial infection." (PMID 31447828, 2019).
peripheral neuropathy (2 papers, 2024 to 2025). A disorder affecting the peripheral nervous system. "Together, the regulation of FCER1G, SYK, and PTK2B on the development of nerve system disease suggests that they most likely contribute to T2DM‐induced peripheral neuropathy." (PMID 38018513, 2024).
PTK2B also shares sentences with these, for which no sentence is quoted: osteosarcoma (8 papers); colon carcinoma (7); pancreatic cancer (7); astrocytomas (5); atherosclerosis (5); chronic myeloid leukemia (5); colorectal cancer (5); breast tumors (4); cardiac hypertrophy (4); ischemic stroke (4); myocardial infarction (4); small cell lung carcinoma (4); triple-negative breast carcinoma (4); adenoma (3); bladder cancer (3); cardiovascular disease (3); diabetes mellitus (3); endothelial dysfunction (3); inflammatory bowel disease (3); liver fibrosis (3); neurological disorders (3); renal fibrosis (3); Stroke (3); adenocarcinoma (2); brain diseases (2); brain tumor (2); chronic lymphocytic leukaemia (2); colitis (2); colorectal adenocarcinoma (2); gastric cancer (2).
A further 99 diseases each share a sentence with PTK2B in 2 papers or fewer.